SMAD1 (SMAD family member 1)
Diseases named in the same sentence as SMAD1 in open-access papers (continued):
Sharing a sentence is not in itself a finding about the gene and the disease.
diffuse large B-cell lymphoma (4 papers, 2010 to 2024). "Previous studies on diffuse large B-cell lymphoma (DLBCL) revealed SMAD1 as a key messenger in the tumor-suppressive signaling axis of TGF-β." (PMID 33567641, 2021). "However, in diffuse large B-cell lymphoma (DLBCL) and Hodgkin lymphoma aberrant loss of SMAD1 expression has been involved in the pathogenesis of the disease." (PMID 39834944, 2024). "Interestingly, high SMAD1 level could activate S1PR2 expression and induce apoptosis in diffuse large B-cell lymphoma." (PMID 34134766, 2021).
fibrodysplasia ossificans progressiva (4 papers, 2020 to 2026). Fibrodysplasia ossificans progressiva (FOP) is a severely disabling heritable disorder of connective tissue characterized by congenital malformations of the great toes and progressive heterotopic ossification that forms qualitatively normal bone in characteristic extraskeletal sites. "Mutations in activin-like kinase 2 (ALK2), e.g., ALK2-R206H, induce aberrant signaling to SMAD1/5/8, leading to Fibrodysplasia Ossificans Progressiva (FOP)." (PMID 38334613, 2024).
lung adenocarcinoma (4 papers, 2016 to 2025). A carcinoma that arises from the lung and is characterized by the presence of malignant glandular epithelial cells. "In lung adenocarcinoma of our patient cohort and public dataset, FSTL1 expression had positive correlation with BMP4-p-Smad1/5/8-Smad4 expression level and loss of FSTL1, BMP4, and Smad4 expression had a similar trend to predict poor prognosis." (PMID 28852126, 2017). "Moreover, frequent decrease of FSTL1-BMP4-p-Smad1/5/8-Smad4 pathway observed in smokers and in ALK-fusion or KRAS mutant adenocarcinoma patients may facilitate the understanding of the molecular pathogenesis of lung adenocarcinoma." (PMID 28852126, 2017).
Obesity (4 papers, 2012 to 2024). Accumulation of substantial excess body fat. "As Ahnak deficiency mediates obesity resistance, we proposed possible mechanism that Ahnak cooperates with Bmpr1α, which regulates the BMP4/Smad1/5 signal transduction." (PMID 30154465, 2018). "We previously found that Ahnak functions in obesity resistance and insulin sensitivity by regulation of Smad1/5 signaling pathways." (PMID 30154465, 2018). "Collectively, our data show that AHNAK promotes adipose tissue development and obesity by potentiating BMP4/SMAD1 signaling and that AHNAK can serve as a novel regulator of metabolic homeostasis." (PMID 26466345, 2015). "Of importance, these parameters were notably decreased whereas the anti-fibrotic biomarkers (the protein expressions of BMP-2 and p-Smad1/5) were significantly increased in mice after reduction in obesity." (PMID 22784636, 2012). "The expressions of fibrotic markers phosphorylated Smad3 and TGF-β were higher, whereas expression of anti-fibrotic phosphorylated Smad1/5 and BMP-2 were lower (all p<0.02); and LVEF was lower, whereas the LV remodeling was higher in obesity than in control and OR (all p<0.001)." (PMID 22784636, 2012).
pancreatic cancer (4 papers, 2018 to 2025). "The enhanced dependence on the BMP/SMAD1/5/9 pathway in SMAD4-deficient contexts could potentially explain why CHRDL1 exhibits more pronounced metastasis-suppressing effects in pancreatic cancer." (PMID 40837015, 2025). "As a BMP antagonist, CHRDL1 desensitizes pancreatic cancer cells to BMP-4, thereby inhibiting BMP-mediated SMAD1/5/9 signaling." (PMID 40837015, 2025).
pulmonary fibrosis (4 papers, 2017 to 2024). Chronic progressive interstitial lung disorder characterized by the replacement of the lung tissue by connective tissue, leading to progressive dyspnea, respiratory failure, or right heart failure. "Additionally, A2AR may play a role in reducing fibrosis involved in cardiac pathological remodelling and pulmonary fibrosis through the Rap1 or BMP7/Smad1/5 signalling pathway." (PMID 38057890, 2023). "Several studies have confirmed elevated BMP2 receptor levels induced by IL-6 signaling can activate SMAD1/5/8 and dampen the SMAD 2/3 pathway in idiopathic pulmonary fibrosis." (PMID 39334820, 2024).
systemic sclerosis (4 papers, 2013 to 2022). A chronic disorder, possibly autoimmune, marked by excessive production of collagen which results in hardening and thickening of body tissues. "Such an imprint pathway might be active in systemic scleroderma fibroblasts of which a subset shows a constitutive activation of the (TGF)β/Alk1/SMAD1 signalling pathway." (PMID 23782569, 2013).
acute myeloid leukemia (3 papers, 2020 to 2024). Acute myeloid leukemia (AML) is a group of neoplasms arising from precursor cells committed to the myeloid cell-line differentiation. "Overall, our data contributes to the understanding of the role of TGF-β signaling in acute myeloid leukemia with KMT2A::AFF1 by showing that SMAD1 loss can influence the growth dynamics and contribute to the pathogenic expression of disease driving factors." (PMID 39834944, 2024).
cervical cancer (3 papers, 2017 to 2022). A primary or metastatic malignant neoplasm involving the cervix. "It was reported that Smad1/5 activation involves in EMT induction and cancer progression, but another study showed that a negative regulator of TGF-β-mediated EMT increases Smad1/5/8 phosphorylation in cervical cancer cells." (PMID 35580109, 2022). "They demonstrated that FAD104, a positive regulator of adipocyte differentiation, suppresses the TGF-β-mediated EMT in cervical cancer cells, with upregulation of Smad1/5/8 phosphorylation and downregulation of Smad2/3 phosphorylation." (PMID 35580109, 2022). "It is necessary to clarify the role and function of Smad1/5/8 activated by TGF-β during EMT of cervical cancer cells." (PMID 29180690, 2017). "To analyse the relationship between these proteins and FAD104 in TGF-β–induced EMT of cervical cancer cells, we clarify the molecular mechanism by which FAD104 regulates the phosphorylation of Smad1/5/8 and Smad3 in the next paper." (PMID 29180690, 2017).
glomerulosclerosis (3 papers, 2011 to 2018). A hardening of the kidney glomerulus caused by scarring of the blood vessels. "In particular, phosphorylation of Smad1 was largely caused by AGE, suggesting that AGE has a critical role for the development of glomerulosclerosis through activation and modulation of Smad1 in MCs." (PMID 30002389, 2018). "Phosphorylation of the Smad1 linker domain, which was partially regulated by Smad3 signaling, attenuated glomerulosclerosis, suggesting that Smad1 linker domain can be used as a target for treating DN." (PMID 30002389, 2018). "In this study, we demonstrated clearly that Smad1 plays a critical role in the production of ECM proteins that subsequently lead to glomerulosclerosis." (PMID 27492138, 2016). "Further understanding of the Src/Smad1 pathway and the molecules involve in this pathway is critical for the clarification of glomerulosclerosis and to pave the way for a strategy to treat progressive glomerulonephritis." (PMID 21445358, 2011). "In the rat proliferative glomerulonephritis model, administration of PP2 completely abolished the phosphorylation of c-Src and Smad1 and resulted in the amelioration of glomerulosclerosis." (PMID 21445358, 2011). "In the present study, we demonstrated that c-Src is activated in experimental proliferative glomerulonephritis and that the reduction of c-Src ameliorates the development of glomerulosclerosis by blocking of the Smad1 signal transduction pathway." (PMID 21445358, 2011). "We previously reported that Smad1 participates in the development of glomerulosclerosis in experimental glomerulonephritis." (PMID 21445358, 2011). "Thus, Smad1 is the key signaling molecule directly involved in the initiation and progression of glomerulosclerosis in DN and other kidney diseases." (PMID 30002389, 2018). "Moreover, we have shown that administration of anti-PDGFβ-receptor (anti-PDGFβR) antibody (APB5) to the mesangial-proliferative model of GN in Thy1 GN rats attenuates glomerular cell proliferation and glomerulosclerosis and Smad1 activation." (PMID 27492138, 2016). "Thus we hypothesized that Smad1 may play a role in the progression towards glomerulosclerosis in GN." (PMID 27492138, 2016). "In Smad1-CKO mice, glomerulosclerosis and intense Col4 staining were markedly reduced after NTS treatment." (PMID 27492138, 2016). "In conclusion, our present study indicates that c-Src activates Smad1-induced ECM production and phenotypic alteration, and is involving in the progression of proliferative glomerulonephritis leading to glomerulosclerosis." (PMID 21445358, 2011). "We previously reported that Smad1 upregulated the expression of Col4 and SMA and thereby participates in the development of glomerulosclerosis in experimental glomerulonephritis." (PMID 21445358, 2011). "We examined the expression of Smad1 and glomerulosclerosis-related proteins in MCs treated with or without probucol." (PMID 30002389, 2018). "Because PDGF is well known to play a key role in the development of glomerulosclerosis, we investigated whether PDGF can activate c-Src/Smad1 signal transduction and increase the synthesis of Col4." (PMID 21445358, 2011). "Moreover, we previously showed that the development of glomerulosclerosis from mesangial proliferation is dependent on PDGF-induced Smad1 activation, but little is known concerning the regulatory mechanisms of Smad1 activation by PDGF in glomerulonephritis." (PMID 21445358, 2011).
Hyperglycemia (3 papers, 2022 to 2024). An increased concentration of glucose in the blood. "The present work shows that hyperglycemia in human macrophages changes the balance between Smad1/5 and Smad2/3-dependent signaling." (PMID 39062148, 2024). "We found that the combination of nicotine and hyperglycemia increased the activation of Smad2/3 and the expression of its target genes Id1 and Id4 but decreased the activation of Smad1/5/8 and the expression of its target gene Snail." (PMID 37415117, 2023). "Western blotting and IHC staining showed that the combination of nicotine and hyperglycemia significantly increased the activation of Smad2/3 and decreased the activation of Smad1/5/8 compared with nicotine or hyperglycemia alone." (PMID 37415117, 2023). "In conclusion, we speculated that BMP-7 could upregulate SnoN mRNA level by activating the classical Smad1/5 signaling pathway, and it also could reduce the ubiquitination of SnoN protein, finally restoring the SnoN protein level to inhibit hyperglycemia-mediated renal tubular epithelial fibrosis." (PMID 35314669, 2022).
neuroblastoma (3 papers, 2018 to 2025). Neuroblastoma (NB) is the most common solid, extracranial childhood tumor. "We treated ATRA-sensitive neuroblastoma cell lines (CHP-134, NB-13, TGW, SK-N-SH) with FK506 or rapamycin for four hours, which in all cases resulted in increased phosphorylation of SMAD1/5/9, indicating an increase in BMP signaling activity." (PMID 40021625, 2025). "Similarly, in the neural crest derived tumor, neuroblastoma, ADAM11 expression is higher than in the normal tissue, with a concurrent increase in Smad1-5 expression and decreases in Sox3 expression." (PMID 37766964, 2023).
rheumatoid arthritis (3 papers, 2008 to 2023). A chronic, systemic autoimmune disorder characterized by inflammation in the synovial membranes and articular surfaces. "Activation of BMP signaling in collagen-induced arthritis as a model of rheumatoid arthritis was studied by immunohistochemistry and Western blot for phosphorylated SMAD1/5 at different time points." (PMID 18816401, 2008).
Stroke (3 papers, 2011 to 2020). Sudden impairment of blood flow to a part of the brain due to occlusion or rupture of an artery to the brain. "Coicis Semen treatment significantly activated the TGF-β1/ALK1/Smad1/5 pathway in the recovery phase of stroke." (PMID 33290255, 2020). "CD31, TGF-β1, ALK-1, Smad1/5 and p-Smad1/5 levels in the penumbra of the ischemic brain were elevated at 7 and 14 days after stroke, and this increase was significantly improved by Coicis Semen administration (P < 0.05)." (PMID 33290255, 2020). "The mechanisms by which Smad1 deletion results in attenuated glial responses and neuronal protection after stroke remain to be determined." (PMID 26317208, 2015). "We found that Smad1 cKO mice at 8 to 10 months of age also exhibited significant improvement in functional recovery at 7 days post-stroke." (PMID 26317208, 2015). "When subjected to I/R injury by transient middle cerebral artery occlusion (tMCAO), Smad1 cKO mice showed enhanced neuronal survival and improved neurological recovery at 7 days post-stroke." (PMID 26317208, 2015). "In both control and Smad1 cKO animals, residual astroglial scarring was visible, but confined to the striatal stroke core, with small necrotic centers sometime observed in control animals." (PMID 26317208, 2015). "Here, we demonstrate that Smad1 deletion in the CNS confers neuroprotection in a cerebral I/R injury model in both young and older mice, thus establishing a novel link between Smad1 and stroke pathophysiology." (PMID 26317208, 2015). "Consistent with our results and in support of a role of Smad1 in mediating canonical BMP signaling in stroke, Noggin, an endogenous BMP antagonist, has been shown to confer protection against ischemic brain injury." (PMID 26317208, 2015). "Smad1 therefore represents a potential novel target for stroke therapy." (PMID 26317208, 2015). "Our data suggest that Smad1-mediated signaling pathway is involved in stroke pathophysiology and may present a new potential target for stroke therapy." (PMID 26317208, 2015). "Since Smad1-/- astrocytes show enhanced antioxidant capacity, and astrocytes can protect against ischemic injury by releasing the antioxidant glutathione, we next sought to test whether Smad1 deletion would attenuate stroke pathophysiology." (PMID 26317208, 2015). "Thus, the observed neuroprotective phenotypes in Smad1 cKO mice at 7 day post-stroke are more likely a result of reduced secondary injury than enhanced neural repair." (PMID 26317208, 2015). "Our data show that Smad1 deletion affects several aspects of astrocytic function, which may contribute to neuroprotection against stroke: i) GFAP expression is elevated in astrocytes in uninjured Smad1 cKO mice." (PMID 26317208, 2015). "Hence, the reduced inflammatory response in Smad1 cKO mice is more likely a result of attenuated stroke pathophysiology than microglial dysfunction." (PMID 26317208, 2015). "Developing strategies to inhibit the Smad1-mediated pathway may represent a novel direction for stroke protection." (PMID 26317208, 2015). "Cresyl violet staining at 24 h post-stroke confirmed the stereotypical morphological changes of acute neuronal damage in control animals, including shrunken cell bodies, pyknotic nuclei, perineuronal vacuolations, and neuronal necrosis, all of which were less prominent in Smad1 cKO mice." (PMID 26317208, 2015). "Our finding of a potential link between astrocyte phenotype (GFAP upregulation and hypertrophic morphology) and stroke protection raises a tantalizing possibility that Smad1 ablation in the CNS may mimic the well-known preconditioning effect in raising the baseline levels of astrocyte reactivity." (PMID 26317208, 2015).
Stroke (continued). "However, the precise functions of BMP/Smad1 signaling in stroke pathophysiology remain unknown; by contrast, its roles in I/R injury outside the CNS have begun to emerge." (PMID 26317208, 2015). "Here, we show that deletion of Smad1, a conserved transcription factor that mediates canonical bone morphogenetic protein (BMP) signaling, results in neuroprotection in an ischemia-reperfusion (I/R) stroke model." (PMID 26317208, 2015). "It is also noteworthy that the current study combines data from both sexes, thus, does not address gender effects in the Smad1 cKO mice after stroke, a topic worthy of future investigation." (PMID 26317208, 2015). "Notably, Smad1 deletion does not seem to prevent astrocytes from mounting a reaction to CNS injury, as in areas of severe ischemia, such as in the striatal stroke core, robust reactive astrocytosis did occur in both mutant and control mice." (PMID 26317208, 2015).
Alzheimer disease (2 papers, 2017 to 2024). A progressive, neurodegenerative disease characterized by loss of function and death of nerve cells in several areas of the brain leading to loss of cognitive function such as memory and language. "The BCL3, CFLAR, SMAD1, and HIF1A genes have been identified to be associated with late-onset Alzheimer's disease." (PMID 28558704, 2017).
amyotrophic lateral sclerosis (2 papers, 2014 to 2024). Amyotrophic lateral sclerosis (ALS) is a neurodegenerative disease characterized by progressive muscular paralysis reflecting degeneration of motor neurons in the primary motor cortex, corticospinal tracts, brainstem and spinal cord. "In FTDC, PIF promotes bone morphogenetic protein pathway (SMAD1, 53-fold) and axonal guidance genes (EPH5) while inhibiting PPP2R2C, negative cell-growth regulator, involved in Alzheimer’s and amyotrophic lateral sclerosis." (PMID 26085845, 2014).
cardiac hypertrophy (2 papers, 2023 to 2025). "Mice with BMPR2 knockout showed reduced Ang II-induced cardiac tissue growth, demonstrating that Ang II can transactivate BMPR2 to activate Smad1 and Smad5, resulting in cardiac hypertrophy." (PMID 39506064, 2025). "Infusion of Ang II for 2 weeks in mice induces the phosphorylation of Smad1 and Smad5 in the carboxyl-terminal, leading to cardiac hypertrophy, which is inhibited by BMPR2 inhibitor, LDN193189." (PMID 39506064, 2025).